MGAM (maltase-glucoamylase)
Diseases named in the same sentence as MGAM in open-access papers (continued):
Sharing a sentence is not in itself a finding about the gene and the disease.
cancer (continued). "Interestingly, MGAM's role varied across these cancers, exhibiting both stimulatory and inhibitory effects on these pathways." (PMID 40881483, 2025). "In the present study, the comprehensive analysis of pooled data from multiple resources, including TCGA, GTEX datasets, Firebrowse, and GSCA databases, has unveiled substantial variations in the expression levels of the MGAM gene across a wide spectrum of cancer types." (PMID 40881483, 2025). "This suggests that MGAM may promote cancer progression through diverse mechanisms, depending on the specific cancer type and its genetic and molecular context which needs further clarification." (PMID 40881483, 2025). "Moreover, abnormal methylation patterns of MGAM were detected in numerous cancer types, underscoring the gene's involvement in cancer biology beyond its transcriptional regulation." (PMID 40881483, 2025). "Notably, MGAM exhibited divergent impacts on cellular processes in different cancer contexts." (PMID 40881483, 2025). "Using RNA‐Seq data from Recount3, Firebrowse, and gene set co‐expression analysis databases, we analyzed the differential expression of MGAM and its paralog MGAM2 across 33 cancer types." (PMID 40881483, 2025). "MGAM and MGAM2 showed differential expression across multiple cancers, with MGAM2 upregulated and MGAM downregulated in gastrointestinal tumors." (PMID 40881483, 2025). "In light of the comprehensive analysis of MGAM and MGAM2 gene expressions within various cancer contexts, it is clear that these genes represented pivotal players in the complex nature of cancer biology." (PMID 40881483, 2025). "In conclusion, our investigation provides robust evidence supporting the critical function of the MGAM and MGAM2 genes in cancer biology." (PMID 40881483, 2025). "Our investigation into the role of MGAM and MGAM2 genes in various cancers has unveiled intriguing insights into their correlation with immune cell infiltration and their potential as diagnostic and prognostic markers." (PMID 40881483, 2025). "Interestingly, the expression pattern of MGAM and MGAM2 seems to be similar in cancers such as DLBC, KIRC, LUAD, and THYM, whereas it seems to have a converse effect in GI cancers such as COAD, READ, CHOL, ESCA, LIHC, and STAD." (PMID 40881483, 2025). "Furthermore, MGAM and MGAM2 were identified as targets of approved antidiabetic drugs, adding another layer to their multifaceted roles in cancer biology and therapeutics." (PMID 40881483, 2025). "Additionally, MGAM expression correlated strongly with CNVs in OV, HNSC, THCA, SKCM, LUAD, BRCA, and LGG cancers." (PMID 40881483, 2025). "Interestingly, MGAM displayed contrasting effects on EMT in STAD and ESCA cancers compared to LIHC, LUSC, and HNSC." (PMID 40881483, 2025). "On the basis of putative cancer-related annotations, two genes, namely ADAM metallopeptidase domain 9 (ADAM9) and maltase-glucoamylase alpha-glucosidase (MGAM), that mapped to CNA regions were selected for further evaluation of their mRNA expression using reverse transcriptase qPCR." (PMID 23405089, 2013).
infection (3 papers, 2019 to 2023). The state of being infected such as from the introduction of a foreign agent such as serum, vaccine, antigenic substance or organism. "However, using receiver operating characteristic curves, we identified four to 48 candidate biomarkers of infection depending on the pathogen, including seven overlapping biomarkers (DSG2, PCBP1, MGAM, APOA4, DPEP1, GOT1, and IGFALS)." (PMID 38193073, 2023).
gastrointestinal disease (1 paper, 2023). A disease that occurs in the gastrointestinal system, excluding the hepatobiliary system. "MGAM is involved in breaking down carbohydrates in the small intestine, and its deficiency has been linked to gastrointestinal diseases." (PMID 38193073, 2023).
MGAM also shares sentences with these, for which no sentence is quoted: -glucoamylase deficiency (3 papers); acute kidney injury (2); Oral Squamous Cell Carcinomas (2); Alzheimer disease (1); amyloidosis (1); bacterial infections (1); benign prostatic hyperplasia (1); bronchopulmonary dysplasia (1); clear-cell renal cell carcinoma (1); diffuse large B-cell lymphoma (1); gastrointestinal disorders (1); gastrointestinal tumors (1); idiopathic interstitial pneumonia (1); ischemic stroke (1); lung carcinoma (1); lung squamous cell carcinoma (1); lymphoid neoplasm (1); malnutrition (1); metastatic tumors (1); mucositis (1); nonalcoholic steatohepatitis (1); oral carcinoma (1); Pan (1); pancreatic adenocarcinoma (1); pituitary adenomas (1); Pompe disease (1); Protein-losing enteropathy (1); sarcoma (1); schizophrenia (1); Strabismus (1).
A further 4 diseases each share a sentence with MGAM in 1 paper.